NOX1 (NADPH oxidase 1)
Diseases named in the same sentence as NOX1 in open-access papers (continued):
Sharing a sentence is not in itself a finding about the gene and the disease.
gastritis (3 papers, 2019 to 2023). Inflammation of the stomach. "We found that SOX2-expressing cells were increased significantly by NOX1/ROS pathway activation in gastritis-associated hyperplastic mucosa." (PMID 30700829, 2019). "In addition, NOX1 expression is elevated in human H. pylori-associated gastritis and GC and H. pylori induces NOX1-derived ROS in guinea pig gastric mucosal cells." (PMID 36125689, 2023). "Notably, expression of Nox1, Noxa1, Cyba encoding p22phox as well as Noxo1 was increased significantly in both mouse models for gastric tumors and gastritis in comparison to wild-type mouse stomach, which suggest the inflammation-dependent activation of the NOX1 pathway." (PMID 30700829, 2019). "In conclusion, we found that NOX1 complex components are upregulated in epithelial cells of both gastritis and gastric tumors, indicating the inflammation-dependent activation of NOX1/ROS signaling in the stomach." (PMID 30700829, 2019). "Accordingly, NOX1/ROS signaling may promote an increase in SOX2-exressing undifferentiated epithelial cells, contributing to the development of gastritis-associated hyperplasia and gastric tumors." (PMID 30700829, 2019). "Since the activation of NOX1 complex is regulated by the protein level and phosphorylation of NOXO1, NF-κB is possibly important for NOX1/ROS pathway activation both in the gastritis and gastric tumors." (PMID 30700829, 2019). "Notably, among significantly activated pathways in K19-C2mE mouse gastritis compared with normal stomach, the SOX2 pathway was downregulated in apocynin-treated MKN45 cells, indicating that SOX2 is a possible target of NOX1/ROS pathway in gastritis tissues." (PMID 30700829, 2019). "Here, we showed that expression of NOX1 complex components, including Noxo1, but not other NOX family members was significantly upregulated in both mouse models for gastritis and gastric tumors, which was associated with increased ROS levels." (PMID 30700829, 2019).
glioma (3 papers, 2016 to 2022). A benign or malignant brain and spinal cord tumor that arises from glial cells (astrocytes, oligodendrocytes, ependymal cells). "Recent research reported that PAK4 interacted with PPARγ to regulate Nox1 in glioma." (PMID 34584017, 2021). "Our preliminary data showed that among the five types of NADPH oxidase (NOX1-5), only NOX4 was induced by PMA in U87MG glioma cells (data not shown)." (PMID 27043542, 2016).
idiopathic pulmonary fibrosis (3 papers, 2020 to 2024). Idiopathic pulmonary fibrosis (IPF) is a nonneoplastic pulmonary disease that is characterized by the formation of scar tissue within the lungs in the absence of any known cause. "Notably, the NOX1/NOX4 dual inhibitor GKT137831 is the only NOX inhibitor that has entered clinical trials [GKT137831 in IPF Patients with Idiopathic Pulmonary Fibrosis (GKT137831), NCT03865927]." (PMID 32605023, 2020).
metabolic syndrome (3 papers, 2015 to 2022). A cluster of metabolic risk factors for CARDIOVASCULAR DISEASES and TYPE 2 DIABETES MELLITUS. "In addition, PDI expression has been shown to be elevated in atherosclerotic lesions, while Nox-1 is reported to be upregulated in mesenteric arteries of mice with metabolic syndrome and contributes to vasodilation of these vessels." (PMID 33806982, 2021).
renal carcinoma (3 papers, 2017 to 2022). A carcinoma arising from the epithelium of the renal parenchyma or the renal pelvis. "In renal cancer cell lines, knockdown of NOX1 expression by siRNA has been found to decrease HIF-2α expression as well as the phosphorylation of Akt and 4E-BP1." (PMID 28330872, 2017). "Studies have shown that NADPH oxidase 1 (NOX1) and NADPH oxidase 4 (NOX4) maintain HIF-2α expression in renal carcinoma through ROS generation, contributing to renal carcinogenesis." (PMID 35624785, 2022).
stomach cancer (3 papers, 2019 to 2024). "Taken together, these results indicate that NOX1/ROS pathway induces increase of SOX2 expression in gastric tumor cells." (PMID 30700829, 2019).
tendinopathy (3 papers, 2022 to 2025). "One of the examples is the increased expression of NOX1 and NOX4 in rat cultured tenocytes and Achilles’ tendons with collagenase-induced tendinopathy concomitant with elevated ROS levels following the stimulation with nicotinamide mononucleotide." (PMID 40023978, 2025). "Both in rat cultured tenocytes and in Achilles’ tendons with collagenase-induced tendinopathy levels of IL6, ROS and NOX1 and NOX4 were increased while SIRT1 and SIRT6 were decreased together with SOD activity." (PMID 40023978, 2025). "HIF-1 has been documented to promote the expression of the NOX family, particularly NOX1 and NOX4, which are highly elevated in oxidative-stress-induced tendinopathy animal models." (PMID 38247510, 2024). "After 2 weeks of treatment, immunostaining revealed significantly suppressed NOX1 and NOX4 levels in the Achilles tendons of the NMN group compared to the control in a collagenase-induced tendinopathy model (p = 0.043 and p = 0.021, respectively)." (PMID 35287653, 2022). "In Achilles tendons with collagenase-induced tendinopathy, NMN increased the mRNA expression of SIRT1 and SIRT6, as well as SOD activity; while suppressing protein expression of NOX1 and NOX4, and mRNA expression of IL6." (PMID 35287653, 2022). "In vitro and in vivo studies by Yamaura and colleagues showed that NMN has antioxidant effects against tendinopathy and promotes the expression of SIRT 1 and SIRT 6, known for their anti-aging and anti-inflammatory roles, while reducing the expression of NOX1, NOX4, Il-6, and ROS." (PMID 38247510, 2024). "During tendinopathy, hypoxia promotes the expression of HIF-1α, NOX1, and NOX4." (PMID 38247510, 2024).
age-related macular degeneration (2 papers, 2022 to 2025). Age-related loss of vision in the central portion of the retina (macula), secondary to retinal degeneration. "In retinal phagocytes, NOX1 is the primary source of ROS and depends on the translocator protein (TSPO) for activation; this NOX1-TSPO activity in microglia has been linked to neurotoxicity and abnormal retinal angiogenesis in age-related macular degeneration in a mouse model." (PMID 41008646, 2025). "In a murine laser-induced choroidal neovascularization (CNV) model to study age-related macular degeneration (AMD), Nox1 knockout resulted in significantly reduced laser-induced vascular leakage and CNV volume without altering laser-induced levels of VEGF and angiopoietin." (PMID 35741081, 2022).
aneurysm (2 papers, 2023 to 2025). Bulging or ballooning in an area of an artery secondary to arterial wall weakening. "Western blot results further confirmed the increased expression of Nox1 in aortas with aneurysm tissues." (PMID 39721498, 2025). "To investigate the expression of Nox1 in aneurysm tissues, we isolated abdominal aortas from ApoE−/− mice that were subcutaneously infused with Ang II for 28 days." (PMID 39721498, 2025). "In mouse models, cigarette smoke exposure is increases ROS and NOX1 which precipitates upregulation of proinflammatory/matrix remodeling genes, leading to vascular smooth muscle cell modulation and aneurysm formation and rupture." (PMID 37600234, 2023).
Arterial thrombosis (2 papers, 2021 to 2025). The formation of a blood clot inside an artery. "Specifically, NADPH oxidase 1 (NOX1)- and NOX2-derived ROS promote platelet aggregation through the Syk–PLCγ–Ca2+ signaling pathway, with NOX2 being essential for arterial thrombosis." (PMID 40599891, 2025).
atopic dermatitis (2 papers, 2021). "Inhibition of NOX1 leads to attenuation of elevated ROS levels in in vitro models of atopic dermatitis (AD) and psoriasis (PSO) in keratinocytes." (PMID 34326922, 2021).
cholestasis (2 papers, 2020). Impairment of the bile flow caused by obstruction within the liver, or outside the liver in the bile duct system. "Setanaxib (GKT831) a NOX1/4 inhibitor which inhibits NADPH oxidases 1 and 4, involved in the development of hepatic inflammation and fibrosis, was shown to improve fibrosis and cholestasis." (PMID 31970467, 2020).
chronic kidney disease (2 papers, 2021 to 2022). Impairment of the renal function secondary to chronic kidney damage persisting for three or more months. "Serum derived from patients with early chronic kidney disease stage 2–3 or chronic kidney disease stage 5 induces NOX1 upregulation along with a robust elevation of reactive oxygen species and calcium deposition in primary rat vascular smooth muscle cells." (PMID 34440716, 2021). "Serum derived from patients with chronic kidney disease induces NOX1 upregulation with an elevation of reactive oxygen species and calcium deposition in primary vascular smooth muscle cells." (PMID 34440716, 2021). "Oxidative stress via NOX1 contributes to vascular calcification in patients with chronic kidney disease, while a NOX1 inhibitor reduced the alteration." (PMID 34440716, 2021). "Oxidative stress via NOX1 contributes to vascular calcification in patients with chronic kidney disease, while a NOX1 inhibitor ML171 reduced the alterations." (PMID 34440716, 2021). "Previous studies suggest the role of oxidative stress produced by NOX1, NOX2, and NOX4 in the vascular smooth muscle cells of chronic kidney disease patients." (PMID 34440716, 2021).
cyst (2 papers, 2018 to 2025). A sac-like closed membranous structure that may be empty or contain fluid or amorphous material. "However, the cyst burden was below the detection threshold limit of ~25 cysts/mouse brain in wild-type, Nox1−/−, and Nox2−/− mice." (PMID 30154263, 2018).
cystitis (2 papers, 2022). Inflammation of the urinary bladder. "We therefore designed the present study to evaluate whether NOX1/4 or NOX2 inhibition (by using GKT137831 or GSK2795039, respectively) improves ROS-generation, bladder hyperactivity, and inflammatory and nociceptive responses related to CYP-induced cystitis in mice." (PMID 36670953, 2022).
diabetic cardiomyopathy (2 papers, 2020 to 2022). Diabetic cardiomyopathy is a disorder of the heart muscle in people with diabetes. "Despite several limitations, our data suggest that NOX1 contributes to the exacerbation of diabetic cardiomyopathy by increasing fibrosis and oxidative stress." (PMID 36225554, 2022). "In brief, these data suggest that NOX1 promotes myocardial fibrosis in diabetic cardiomyopathy by activating the TLR2/NF-κB pathway." (PMID 36225554, 2022). "As a result of these findings, NOX1 appears to be a promising therapeutic target for diabetic cardiomyopathy." (PMID 36225554, 2022). "Overall, our new findings suggest that NOX1 may have important translational value in the treatment of diabetic cardiomyopathy." (PMID 36225554, 2022). "In summary, we demonstrated that NOX1 promoted myocardial fibrosis and cardiac dysfunction via activating the TLR2/NF-κB pathway in diabetic cardiomyopathy." (PMID 36225554, 2022). "In summary, we demonstrated that NOX1 induced activation of the TLR2/NF-κB pathway and increased reactive oxygen species production accumulation, which ultimately increased myocardial fibrosis and deteriorated cardiac function in diabetic cardiomyopathy." (PMID 36225554, 2022). "We speculated that NOX1 promoted diabetic cardiomyopathy independent of blood glucose levels." (PMID 36225554, 2022).
endotoxemia (2 papers, 2016 to 2023). "Here, we used in vivo imaging in combination with inhibitor studies and germ-free conditions to conclusively identify NOX1 as essential superoxide generator for microbiota-dependent peroxynitrite production in homeostasis and during early endotoxemia." (PMID 37820403, 2023).
experimental autoimmune encephalomyelitis (2 papers, 2015 to 2016). An autoimmune demyelinating disease of the central nervous system that is produced experimentally in animals by the injection of homogenized brain or spinal cord in Freund's adjuvant. "Here, we employ intravital NAD(P)H fluorescence lifetime imaging to detect functional NADPH oxidases (NOX1–4, DUOX1, 2) and, thus, to identify the cellular source of oxidative stress in the CNS of mice affected by experimental autoimmune encephalomyelitis (EAE) in the remission phase of the disease." (PMID 27014271, 2016).
gastric adenocarcinoma (2 papers, 2020 to 2023). "In gastric adenocarcinoma, NOX1 staining was strong in the apical and luminal surfaces of the malignant cells." (PMID 32428030, 2020).
gastric ulcer (2 papers, 2019 to 2022). An ulcerated lesion in the mucosal surface of the stomach. "Interestingly, ethanol-induced gastric ulcer was associated with Nrf2 downregulation, which was correlated with NOX-1, 2 NOX-4, and HMGB1 upregulation, and was significantly reversed by RK pre-treatment." (PMID 31404064, 2019). "In the present study, the expression of NOX-1 and NOX-4 in gastric tissues was significantly higher in the ethanol positive ulcer group compared to the control group and thus might contribute to gastric ulcer pathogenesis." (PMID 31404064, 2019).
hearing loss (2 papers, 2022 to 2025). "Note also that the similarities of the protective effect of NOX3 deficiency and p22phox deficiency suggest that there is not a major role of other p22phox-dependent NOX isoforms (i.e. NOX1, NOX2, and NOX4) in the pathophysiology of noise induced hearing loss." (PMID 35273964, 2022).
hepatic cancer (2 papers, 2021 to 2023). "In a diethylnitrosamine (DEN)-induced mouse liver cancer model, Nox1-/- mice developed significantly fewer and smaller tumors than those of WT mice, which contributed to the NOX1 deficiency in macrophages, not hepatocytes or hepatic stellate cells." (PMID 36830722, 2023).
influenza (2 papers, 2013 to 2016). An acute viral infection of the respiratory tract, occurring in isolated cases, in epidemics, or in pandemics; it is caused by serologically different strains of viruses (influenzaviruses) designated A, B, and C, has a 3-day incubation period, and usually lasts for 3 to 10 days. "This pattern of expression of Nox1 in the lung places the enzyme at primary sites to orchestrate the inflammation caused by an influenza infection." (PMID 23577160, 2013). "Although some ROS inhibitors have shown immunomodulatory effects, based on our findings, the use of Nox1-selective inhibitors should be explored as an adjunct therapy (e.g., along with antivirals) to decrease the mortality and morbidity associated with influenza." (PMID 26910342, 2016). "In a previous study, Nox1 was shown to modulate influenza-induced inflammation in the early phase (days 3–7) post-infection (p.i.)with a non-lethal dose of influenza." (PMID 26910342, 2016). "Results suggest that NADPH oxidase 1 inhibitors may be beneficial as adjunct therapeutics during acute influenza infection." (PMID 26910342, 2016). "However, the levels of all the cytokines and chemokines examined, with the exception of IFN-γ and IL-10 were elevated in Nox1−/y mice following influenza infection and to a greater extent (≥2–3 fold) than in WT mice." (PMID 23577160, 2013). "Our findings might explain why ROS scavengers generally fail to provide significant protection against influenza because they are likely to remove both the detrimental toxic effects of Nox2-derived ROS and the protective properties of Nox1-derived ROS." (PMID 23577160, 2013). "However, the influence of Nox1 after a lethal challenge of influenza infection has not been reported." (PMID 26910342, 2016).
intestinal tumor (2 papers, 2019). "Furthermore, NOX1 is activated in intestinal tumor cells by Wnt-induced Rac activation, another component of NOX1 complex, which further induces expression of stem cell signature in cancer cells." (PMID 30700829, 2019).
intrahepatic cholangiocarcinoma (2 papers, 2025). A carcinoma that arises from the intrahepatic bile duct epithelium in any site of the intrahepatic biliary tree. "In intrahepatic cholangiocarcinoma (ICC), the gut microbiota can regulate the ALK5/NOX1 signaling axis by altering host glutamine metabolism, ultimately inhibiting ferroptosis in tumor cells." (PMID 41201667, 2025).
kidney (2 papers, 2016 to 2020). "Apocynin, a nonspecific NOX inhibitor, ameliorated the histological damages after IRI by reducing oxidative stress markers, demonstrating that NOX1 was associated with kidney injury and downregulation of NOX could prevent kidney damage." (PMID 32967113, 2020).
lymph node metastasis (2 papers, 2021 to 2023). "Furthermore, NOX1 expression was associated with tumor size and lymph node metastasis." (PMID 33968728, 2021).
metastatic melanoma (2 papers, 2016 to 2023). A melanoma that has spread from its primary site to another anatomic site. "In melanocytic lineages, Nox1, Nox4, and Nox5 are expressed; Nox4 expression is significantly higher in a subset of metastatic melanoma tumors, while in primary and metastatic melanoma tissues, Nox1 is not differentially expressed." (PMID 37189846, 2023). "Collectively, these data suggest a role of eNOS, NOX1 and NOX4 in metastatic melanoma." (PMID 27756874, 2016).
migraine (2 papers, 2022 to 2025). "Accumulating evidence suggests that Nox1 is involved in the processing of inflammatory and neuropathic pain as well as migraine-related pain." (PMID 35740059, 2022). "In addition, a role of Nox1 in glyceryl-nitrate-induced migraine-related pain and ethanol-evoked neuropathic pain processing has been described." (PMID 35740059, 2022). "The shared pathways, such as those regulated by Il1b, Nox1, and Lcn2, are involved in both ferroptosis and immune responses, suggesting that targeting these pathways could modulate multiple aspects of the comorbid migraine and TMDs." (PMID 41465107, 2025).
nasal polyp (2 papers, 2024). "The expression of NOS2, NOX1, HO-1 and SOD2 was increased in nasal epithelial cells and macrophages derived from nasal polyp tissue." (PMID 38756779, 2024).
osteosarcoma (2 papers, 2014 to 2015). A usually aggressive malignant bone-forming mesenchymal neoplasm, predominantly affecting adolescents and young adults. "Studies of osteosarcoma cells with mitochondrial gene knockout (q0) revealed that the inactivation of mitochondrial genes leads to downregulation of Nox1 and that the transfer of wild-type mitochondrial genes can restore Nox1 expression." (PMID 25617620, 2015). "Studies of mitochondrial gene knockout osteosarcoma cells (q0) revealed that the inactivation of mitochondrial genes leads to downregulation of Nox1 and that the transfer of wild-type mitochondrial genes can restore Nox1 expression." (PMID 25536219, 2014).
primary biliary cholangitis (2 papers, 2021 to 2023). Primary biliary cholangitis (PBC) is a chronic and slowly progressive cholestatic liver disease of autoimmune etiology characterized by injury of the intrahepatic bile ducts that may eventually lead to liver failure. "The NOX1/ NOX4 inhibitor setanaxib, which indirectly affects ENaC, is tested in clinical phase 2 and 3 trials for therapy of primary biliary cholangitis, liver stiffness and squamous cell carcinoma of the head and neck." (PMID 37175488, 2023).
rhabdomyosarcoma (2 papers, 2021 to 2022). A rare aggressive malignant mesenchymal neoplasm arising from skeletal muscle. "In the rhabdomyosarcoma cell (Dächert and Ehrenfeld, 2020) and non-small lung cancer cell model, NOX1 can affect lipid peroxidation, ROS production, and other aspects to participate in ferroptosis signal transduction." (PMID 35664309, 2022). "GKT137831, an inhibitor of NOX1, reduces Erastin-induced ROS ferroptosis of rhabdomyosarcoma cells." (PMID 34369274, 2021).
sickle cell disease (2 papers, 2018 to 2020). Sickle cell anemias are chronic hemolytic diseases that may induce three types of acute accidents: severe anemia, severe bacterial infections, and ischemic vasoocclusive accidents (VOA) caused by sickle-shaped red blood cells obstructing small blood vessels and capillaries. "Recently, activity and catalytic subunits of NOX1 and NOX2 were identified in RBCs of patients with sickle cell disease." (PMID 31838004, 2020).